TNF (tumor necrosis factor)
Diseases named in the same sentence as TNF in open-access papers (continued):
Sharing a sentence is not in itself a finding about the gene and the disease.
tumor (continued). "Taken together, our data suggested that TNF-α in PDAC is tumor-promoting, a maker of survival prediction, and more importantly a potential target for treatment." (PMID 27835602, 2016). "Recent studies have shown that LPS-induced metastatic growth response depends on both TNFα production by host hematopoietic cells and NF-κB activation in tumor cells." (PMID 27057094, 2016). "Increasing lines of evidence suggest that TNF-α regulates many of the critical processes of tumor promotion and progression." (PMID 26989335, 2016). "Cytokines such as tumor necrosis factor-α and interleukin-1β released by tumor cells activate the tissue factor (TF)." (PMID 27264137, 2016). "The levels of IL-6, IL-12p70 and TNF-α were substantially increased compared to PBS-treated tumor-bearing mice." (PMID 27008707, 2016). "Targeted delivery of TNFα or IFNγ by TCP-1 peptide exhibited better antitumor activity than unconjugated format by inducing more tumor apoptosis and also enhancing antitumor immunity shown by increased infiltration of T lymphocytes inside the tumor." (PMID 27342639, 2016). "In particular, the Hes1-mediated suppression of Pparg perpetuates the autocrine inflammatory activity of tumor pancreatic cells, inducing the production of inflammatory mediators, such as TNF- α, IL-6 and IL-1β." (PMID 27929540, 2016). "Adiponectin can also directly inhibit tumor necrosis factor α (TNF-α), involved in tumor cell proliferation and angiogenesis." (PMID 27187365, 2016). "TNF treatment does activate NF-κB in tumor cells, as judged by increased levels of the phosphorylated form of the p65 subunit (NF-κBp65P-Ser276) and this was reduced by PDTC treatment." (PMID 27362805, 2016). "Together with TNF-α, IL-1β also increases NF-κB transcription thus increasing tumor adhesiveness, invasion and angiogenesis." (PMID 26896068, 2016). "TNF-α activated AD-MSCs or irradiation significantly decreased the tumor size compared to naïve MSCs or naïve MSCs with irradiation groups (P < 0.05)." (PMID 27329316, 2016). "In vivo, EMT is induced by a range of factors in the tumor microenvironment among which TNFα and TGFβ have been shown to induce EMT in multiple cancer types." (PMID 27777765, 2016). "In conclusion, this study is the first to demonstrate that TNF‐α, a key mediator in the inflammatory tumour microenvironment, strongly up‐regulated CXCR2 and CXCR3 to enhance migration, invasion, EMT and sphere formation of RCC cells." (PMID 27297979, 2016). "MSC treatment with TNF-alpha also resulted in increased MCP-1 expression, which subsequently induced chemoattraction of monocytic immune cell infiltrate, including tumor-associated macrophages." (PMID 27515302, 2016). "TNF-α is a pivotal cytokine involved in several processes including inflammation, cellular homeostasis and tumor progression." (PMID 27429011, 2016). "The lymphocyte, the main component of tumor immunity, can induce natural killer lymphocytes and stimulate giant cells in tumors to release cytokines, including interferons and TNF-α, resulting in tumor shrinkage." (PMID 27438563, 2016). "Immature neutrophils that are released from BM as a result of tumor-driven emergency myelopoiesis were shown to become activated with cytokines released in tumor microenvironment (GM-CSF, IL-4, TNF-α) and acquire molecular features characteristic for DCs." (PMID 28066438, 2016). "Three weeks after inoculation, the tumor volume in mice undergoing anti-TNF treatment reached only 200 mm3, as compared to 500–600 mm3 in the control group." (PMID 27148266, 2016). "And it acted as tumor suppressor by regulating TNF-α induced apoptosis and metabolism in cancer cells." (PMID 27829861, 2016). "These multiple lines of evidence support the idea that pro-inflammatory stimuli, such as IL-1β, IL-6, IL-8 and TNF-α can lead to the activation of Notch signaling with a tumor-promoting effect on epithelial cells." (PMID 27929540, 2016).
tumor (continued). "When IHIC from bacterial-treated animals were cultured with tumor cells, the level of TNF enlarged, whereas the concentration of IL-2 decreased with respect to the unexposed culture from the same group." (PMID 26973649, 2016). "Recently, it was revealed that the levels of VEGF and TNF-α in serum of tumor bearing mice were higher than the control group after implanting 4T1 cells for 10 days, but the CCL2 level was increased quickly after implantation." (PMID 26794215, 2016). "The purpose of these studies was to determine if relative MUC16 expression correlated with TNFα or IFNγ expression, independently of tumor stage or grade." (PMID 26918940, 2016). "Our study expands the role of miR-28 to that of an indirect tumor suppressor by decreasing the phenotype of exhaustion and regulating the cytokine IL-2 and TNF-α secretion." (PMID 27447564, 2016). "Tumor-free mice in each group, despite receiving TNF blockers, showed the same frequency of CD11b+Gr-1+ myeloid cells, at approximately 8–10% of total blood leukocytes." (PMID 27148266, 2016). "It is noteworthy that although TNFα has been described to be tumor suppressive, chronic expression of TNFα confers tumor promoting functions in the colon by acting on IECs to activate NF-κB-dependent tumorigenic cascades." (PMID 27344176, 2016). "Experimentally, the expression of genes associated with T cells (TCRa) and the secretion of cytokines related to their biological function (IFNG and TNFα) were measured in samples obtained from homogenized tumor samples." (PMID 28101055, 2016). "HER2-pulsed DC vaccination will also boost effectiveness of anti-HER2 immunity by increasing IL-12 production, which increases T cell functionality by polarizing T cells into the INF-γ and TNF-α secreting Th1 phenotype in vivo, promoting anti-tumor immunity." (PMID 27766079, 2016). "In this study, we evaluated the effects of systemic TNF ablation on tumor-induced expansion of MDSCs in vivo using TNF humanized (hTNF KI) mice." (PMID 27148266, 2016). "Anti-TNF-α treatments resulted in decreased cell viability in both PDAC tumor cells and pancreatic satellite cells in similar dose in vitro." (PMID 27835602, 2016). "In order to compare possible in vivo anti-tumor effects of TNF blockers used in clinic, we utilized an experimental model of humanized (hTNF KI) mice, endogenously producing human but not mouse TNF." (PMID 27148266, 2016). "Inhibiting of TNF-α with anti-TNF-α antibodies reduced both tumor and stromal components, suppressed the inflammatory tumor microenvironment, resulting in synergistic effects with chemotherapy in a PDAC pre-clinical model." (PMID 27835602, 2016). "The analysis of inflammatory markers (TNF-α) in tumor indicated that BF-rTK + GCV significantly inhibited TNF-α expression." (PMID 27464624, 2016). "In vivo results showed that TNF-α preactivated AD-MSCs combined with irradiation decreased tumor size and increased survival rate in tumor bearing mice." (PMID 27329316, 2016). "This network, which we named the “TNF network”, has paracrine actions within the tumor microenvironment, influencing angiogenesis and the immune cell infiltrate." (PMID 26871292, 2016). "Mechanistically, IL-17A activates the NF-κB pathway in CRC cells, thereby driving tumor survival and growth [see also tumor necrosis factor (TNF)]." (PMID 27148488, 2016). "Mechanisms underlying the anti-tumor properties of MBS included induction of apoptosis (Bax and capase-8), increase of anti-tumor cytokines (TNF-α and IFN-β), promotion of IFN-γ production, and upregulation of cell-mediated immunity through immunopolarization." (PMID 26978396, 2016). "We measured the level of TNF-α secretion by macrophages stimulated with MIC3 because TNF-α was first described as a factor secreted by macrophages that can induce intense tumour necrosis." (PMID 28000706, 2016).
tumor (continued). "But AEG-1 overexpression did induce macrophages to produce crucial inflammatory factors such as IL-6 and TNF-α who are important in promoting tumor progression, invasion and metastasis." (PMID 27793010, 2016). "Tumor size in mice which received TNF-α preactivated AD-MSCs combined with irradiation was measured in comparison to the rest of mice (P < 0.01)." (PMID 27329316, 2016). "Since inflammation plays an important role in tumor development, which mainly acts through the medium of a number of inflammatory cytokines, such as IL‐1β and TNF‐α." (PMID 27734611, 2016). "We also observed reduced expression of TNF-alpha and IL-6 in silibinin-treated cancer cells as well as in tumor tissues from tumor-bearing mice treated with silibinin." (PMID 26510913, 2015). "Poor pharmacokinetics and resistance within some tumor cell lines have been the major obstacles during the preclinical or clinical application of TRAIL (tumor-necrosis-factor (TNF)-related apoptosis-inducing ligand)." (PMID 26445897, 2015). "A Th2-polarized T cell response, characterized traditionally by the cytokine IL-4 but also TNF-α and IL-6, has been shown to support tumor growth." (PMID 26207636, 2015). "In the same manner, MCs can participate in tumor rejection, producing and releasing TNF-α and molecules such as interleukin 1 (IL-1), IL-4, and IL-6 that kill tumor cells." (PMID 25648323, 2015). "Rosemary extracts had a more significant capability to inhibit IL-1 and TNF-α on macrophages, while ginger extracts showed the highest anti-inflammatory activity on the J774 tumor cell line." (PMID 26511466, 2015). "There are many cytokines secreted by aHSCs that are associated with tumor invasion and metastasis, including HGF, EGF, IL-1, IL-2, IL-6, MMP-2, MMP-9, TGF-β, TNF-α, VEGF and members of the Wnt signaling family." (PMID 26517671, 2015). "Mounting evidence suggests that TNFα is important for antitumor immunity, as shown by experiments where tumor immunotherapy with polyI:C required TNFα for treatment success." (PMID 26635798, 2015). "This response was especially prominent when PDT (60 μM ZnPC-ETLs) induced complete tumor cell death, at which point pro-inflammatory signaling by tumor cells was abrogated (TNF-α and CCL2)." (PMID 26307977, 2015). "TNF-α expression was also decreased in the tumor tissues of the ApcMin/+;CD11b−/− mice compared with ApcMin/+ mice, as analyzed by immunoblotting." (PMID 26526388, 2015). "This cross talk is enforced by the significant correlation between TNF-α, NO, nitrotyrosine, and the carbonyl content between tumor and its matched plasma sample." (PMID 26697139, 2015). "This antitumour action of TNF-α is likely due to hyperpermeability of tumour blood vessels, leading also to increased accumulation of CDDP in the tumours." (PMID 25810699, 2015). "Those activated macrophages then produce proinflammatory cytokines, such as TNFα, in a tumor microenvironment." (PMID 26167165, 2015). "Expression of inflammatory cytokines such as IFN-γ, TNF-α, and IL-2 as well as IL-10 expression in draining lymph nodes (LNs) was significantly reduced in kCYC mice after tumor inoculation." (PMID 26098776, 2015). "Systemic inflammatory cytokines, such as tumor necrosis factor α (TNFα), interferon γ (IFNγ), and Toll-like receptor 3 ligands, stimulate the expression of a series of intra-tumor chemokines." (PMID 26057470, 2015). "NF-κB plays a critical role in the regulation of proteins involved in the cell survival (Bcl-2, XIAP), proliferation (cyclin-D1), invasion (MMP-9, RANKL), angiogenesis (VEGF), and inflammation (COX-2, TNF-α), all contribute to the tumor progression." (PMID 26487364, 2015). "This represents the first report associating silibinin with FAT10 and demonstrating that silibinin can modulate TI-induced CIN, apoptosis sensitivity and suppressing TNF-α-induced tumor growth." (PMID 26142316, 2015).
tumor (continued). "Addition of TNF-α to electrochemotherapy prolonged tumour doubling time for 5.5 days in comparison to electrochemotherapy treatment alone throughout the tested concentration range." (PMID 25810699, 2015). "Pro inflammatory cytokines such as interleukin-6 (IL-6) and tumour necrosis factor alpha (TNF-α) have been suggested to play a certain role in the variety of tumours." (PMID 25858079, 2015). "In contrast to Bglap, TNF-α plays an anti-tumor role, and it is able to inhibit the expression of Bglap." (PMID 26266941, 2015). "Second, in contrast to cultured cells in vitro, TQ induced tumor NF-κB reporter activity and mRNA levels of the key NF-κB targets, IL-1β and TNF-α, in drug-treated mice." (PMID 26215403, 2015). "M1 macrophages are known to act as anti-tumor cells due to their high expression of iNOS, nitric oxide, and inflammatory cytokines such as TNF-α and IL-1." (PMID 26474279, 2015). "The aim of this study was to investigate the correlation of serum IL-6 and TNF-α levels on tumour recurrence in patients with OSCC in order to identify potential biomarkers for early detection of disease recurrence." (PMID 25858079, 2015). "Inflammatory cytokines such as TNF-α influence inflammation, apoptosis and tumour development through regulation of the kinase IKKβ." (PMID 25849741, 2015). "In vitro incubation of tumor cells and PBMC with L-MTP-PE induced tumor cytolysis, in a process that was shown to be dependent on TNF-α production by monocytes and macrophages." (PMID 29061951, 2015). "hCG-conditioned tumor cell supernatants induced heightened secretion of IL-6 and TNF-α from peripheral blood adherent cells and secreted IL-6 imparted chemo-resistance to naïve tumor cells." (PMID 26608647, 2015). "The levels of cytokines and chemokines, including IL-1β, IL-6, GM-CSF, G-CSF, MCP-1 and TNF-α, were much higher in tumour tissue lysates than in non-tumour tissue." (PMID 26581194, 2015). "This, in turn, activates transcription of pro-inflammatory factors including COX-2, IL-6, IL-1β, and TNFα, which promote tumor growth and progression through various mechanisms." (PMID 26107623, 2015). "Administration of TNF-α before the electrochemotherapy resulted in longer tumour growth delay and increased tumour curability, and was significantly more effective than TNF-α administration after the electrochemotherapy." (PMID 25810699, 2015). "Several cytokines such as macrophage migratory inhibitory factor (MIF), TNF-α, IL-6, IL-17, IL-12, IL-23, IL-10, and TGF-β have been associated with both experimental and human cancers and can either promote or inhibit tumor development." (PMID 26511466, 2015). "Upon co-culture with tumor cells, the concentration of TNF-α mRNA increased significantly in HFs in both types of co-culture, suggesting that YKL-40 does not influence TNF-α expression." (PMID 26418748, 2015). "Anthracycline and cyclophosphamide (AC) regimen enhances production of tumor necrosis factor-α (TNF-α) from tumor stromal cells and endothelial cells." (PMID 26078490, 2015). "First we demonstrated that in C4-2 CRPC tumor cells, various modes of androgen deprivation de-repress TNF mRNA expression, leading to secretion into the media." (PMID 26327448, 2015). "Due to the toxicity of the combination TI in mice, we thus focused on the role of silibinin in modulating only TNF-α induced tumor growth through FAT10." (PMID 26142316, 2015). "Taken together, our results indicate that TNFα released by tumor cell-activated macrophages is critical for increased MCP-1 production by tumors cells." (PMID 26167165, 2015). "This tumour microenvironment produces various factors, such as TNFα, TGFβ, Wnt, and HIF-1α, all of which stimulate a transient epithelial-mesenchymal transition (EMT) to promote cancer progression, invasion, and metastasis." (PMID 26508818, 2015).
tumor (continued). "In fact, both VEGF and TNF-α are part of a repertoire of molecules responsible for a number of events involved in tumor progression (angiogenesis, macrophage recruitment, proliferation, and metastasis)." (PMID 26158775, 2015). "M1 macrophages will develop an anti-tumor response by producing inflammatory molecules (IL-6, IL-12, IL-23, and TNF-α) and ROS, NO, and TNF." (PMID 25853091, 2015). "Because IL-8 is a chemokine that promotes tumor angiogenesis, we further analyzed the levels of secreted IL-8 protein in MSCs treated with recombinant IL-1β (30 ng/mL) and TNF-α (20 ng/mL) using ELISA." (PMID 26517517, 2015). "Theaddition of TNF-α improves the accumulation of chemotherapeutic drugsselectively in the tumor up to three- to six-fold in rat models." (PMID 25897826, 2015). "In this report, we demonstrated that tumor-induced myostatin in turn induced TNF-α, thus activating calcium-dependent and proteasomal protein degradation." (PMID 25797259, 2015). "The flow cytometry analysisof tumor tissues suggested that TNF-α secreted byCD11b+F4/80+ macrophages increased five timesas compared with the control group." (PMID 26098663, 2015). "TNFα is an inflammatory cytokine with pleiotropic effects, including direct killing of tumor cells via TRAIL (TNFα-Apoptosis-Inducing-Ligand)." (PMID 25592450, 2015). "MoDCs originated from circulating monocytes in response to MSU + Msmeg treatment, expressed iNOS, TNFα, and IL-12 and were necessary for the priming of tumor-specific CD8+ T cells." (PMID 26635798, 2015). "We then determined if silibinin can modulate tumor growth by gavaging the mice with 100 mg/kg dose of silibinin for 5 days a week for 7 weeks after tumor graft and TNF-α administration." (PMID 26142316, 2015). "Those that are mostly TIM-3+ were shown to support the development of exhausted CD8+ T cells and limit the expansion of effector T cells secreting IFN-γ and TNF-α within the tumor microenvironment." (PMID 26492563, 2015). "Some cancer patients present high serum levels of TNF-a, IL-6, and IL-1 which correlate positively with the progression of some tumours." (PMID 26508818, 2015). "In general, skeletal muscle atrophy results from overexpression of TNF-α and myostatin, which up-regulates calcium-activated and ubiquitin-proteasome systems in tumor mice." (PMID 25797259, 2015). "In the present study, results of flowcytometry suggested that the production of TNF-α was increased and secretedfrom the infiltrated macrophages in tumor microenvironment in response toλ-carrageenan stimulation." (PMID 26098663, 2015). "TNFα concentrations were measured in nine tumour secretions, collected in phosphate buffered saline (PBS), using ELISA." (PMID 26690506, 2015). "We show that macrophages from regressing tumors can kill tumor cells in two ways: phagocytosis and TNFα release." (PMID 26337837, 2015). "Cytokines such as TNFα and interleukins, which are produced by both tumour cells and surrounding cells trigger NF-κB signalling, consequently causing the release of TGF-β, an inducer of EMT." (PMID 26508818, 2015). "Further, these studies have not made clear how much TNFα modulation is required for efficacy and what the chronic implications are for the innate immune system given the importance of TNFα in host defense and tumor growth control." (PMID 26436670, 2015). "The intravenous administration of DAB-LF, DAB-LFC and DAB complexed to TNFα expression plasmid resulted in tumor regression of A431 tumors." (PMID 25933695, 2015). "The development of TNF α therapy relies on amelioration of the toxicity seen with systemic therapy and thereby enhancing tumor responses through higher TNF α doses." (PMID 26337231, 2015). "Our results demonstrated that TNF-α, produced by myeloid cells, acts as a tumor-promoting factor that can significantly promote tumor growth in the ApcMin/+ mice." (PMID 26526388, 2015).